IFITM3P6 (IFITM3P pseudogene 6)
Gene: Transcribed processed pseudogene on chromosome 12 (47,135,498 to 47,135,901, reverse strand). Ensembl gene ENSG00000258352.
Diseases named in the same sentence as IFITM3P6 in open-access papers:
IFITM3P6 is named in the same sentence as 3 diseases in open-access papers, as found by Europe PMC text mining. Sharing a sentence is not in itself a finding about the gene and the disease. The quoted sentences say what the papers report.
acute myelocytic leukemia (2 papers, 2022 to 2024). "For instance, a study in the context of acute myelocytic leukemia showed that FLT3LG, along with IFITM3P6, correlates with T-cell activation in the bone marrow microenvironment and impacts patient survival." (PMID 39465855, 2024).
leukemia (1 paper, 2022). A malignant (clonal) hematologic disorder, involving hematopoietic stem cells and characterized by the presence of primitive or atypical myeloid or lymphoid cells in the bone marrow and the blood. "In general, our results demonstrate that IFITM3P6 and FLT3LG might serve as prognostic markers in AML and may be used as potential therapeutic targets for the treatment of leukemia in the future." (PMID 36081495, 2022).
tumor (1 paper, 2022). "Whether these key genes could exert function on AML cells directly, such as the landscape of exosome of IFITM3P6 and/or miR-6748-3p secreted by T cells to interact with tumor cells, these questions remain to be explored." (PMID 36081495, 2022).